CD4 (CD4 molecule)
Diseases named in the same sentence as CD4 in open-access papers (continued):
Sharing a sentence is not in itself a finding about the gene and the disease.
tumor (continued). "The intracellularly stored IL-2Rγ subunit is expressed primarily by hematopoietic cells, some tumor cells, and by CD4+ T only during activation, whereas the dimeric IL-2Rβγ receptor is expressed by memory CD8+ cells, naïve, T, and NK cells." (PMID 36835413, 2023). "Although some solid cancers can be induced to express MHC-II, the extent to which this enables direct recognition by tumor-specific CD4+ T cells is unclear." (PMID 36512410, 2023). "Their efficiency can be confirmed by the presence of CD8+ epitopes that would eventually trigger CTL anti-tumor immunity consequences, alongside CD4+ epitopes aimed at T-helper cell stimulation." (PMID 38140187, 2023). "The results are strongly consistent with our findings suggesting that NSD2 regulates various immune molecules in the tumor microenvironment of PCa, thereby affecting CD4+ and CD8+ T immune cell infiltration." (PMID 38062230, 2023). "Consistent with known roles for CD4+ T cells in recruiting and activating tumor-suppressive itICs13, CD4+ T cell depletion also blocked l-fuc-induced increases in total itICs, including intratumoral NK cells, DCs and CD8+ T cells, observed in control mice." (PMID 36690875, 2023). "TAM2 induces CD4 T cell differentiation into tumor-promoting Tregs while promoting Treg aggregation in the tumor to suppress the antitumor response." (PMID 37628967, 2023). "The earliest evidence of this was studies by Jim Allison and Paul Antony showing that tumor-specific CD4 T cells transferred into lymphopenic hosts developed a cytotoxic phenotype upon tumor challenge." (PMID 37654482, 2023). "The cytotoxic CD8+ T cells are assisted by CD4+ T helper cells through the secretions of cytokines, that build up the anti-tumor response." (PMID 37104271, 2023). "Compared with S100 monotherapy, CD4+ T cells showed little effect on the anti-tumor immunity of S100; whereas with the addition of αTim-3, CD4+ T cells contributed to an anti-tumor response." (PMID 37771774, 2023). "CD4+ T cells, which act as helper cells, possess the capacity to enhance the anti-tumor immune response of CD8+ T cells." (PMID 38078879, 2023). "After sacrificing the tumor-bearing mice, CD4+T cells of the spleen were separated and purified by immune magnetic beads, and the purity of CD4+T cells was 96.0%." (PMID 37274637, 2023). "Tumor-infiltrating T lymphocytes, especially CD4+ and CD8+ T cells, play an adaptive immune role in HCC progression." (PMID 35693941, 2022). "In our studies, we consistenly observed higher frequency of PD-1+ cells in tumor infiltrating CD4+ and CD8+ T cells when IFNAR1 was blocked." (PMID 36311701, 2022). "The results showed that resting CD4+ T cells had the highest level of infiltration than other tumor immune cells in both BCG responders and failures." (PMID 36119059, 2022). "The immune cell dependence was tested on three major immune cell populations (CD8+ T cells, CD4+ T cells and macrophages) in tumor microenvironment." (PMID 36068198, 2022). "Lymphocytes isolated from the respective tumor tissues contained a significantly higher percentage of TIM-3+ CD4 T cells than those from peripheral blood." (PMID 36359346, 2022). "The superior antitumor response following HER2-DC1 i.t. in combination with anti-HER2 antibodies involves tumor infiltration of CD4+ and CD8+ T cells, B cells, NKT cells and NK cells." (PMID 35710296, 2022). "Since the functionality of T cells is important for anti-tumor activity, we investigated the cytokine production of both the CD4+ and CD8+ T cells." (PMID 36439126, 2022). "Our results demonstrated that DEmlncRNAs show a positive relationship with tumor-infiltrating immune cells such as neutrophils and monocytes, while negatively correlated with CD4+ and CD8+T cells." (PMID 35852867, 2022).
tumor (continued). "We showed that tumor-infiltrating PD-1hiCD39+ memory CD4 T cells are exhausted; tumor-Ag-specific; and, in response to anti-PD-1, enhance dendritic cells maturation, leading to tumor-Ag-specific CD8 T cells’ expansion." (PMID 35954341, 2022). "Duvelisib is an oral dual PI3Kγδ inhibitor that targets both tumor and microenvironment cells as PI3Kγ is expressed by CD4+ T-cells and M2 macrophages." (PMID 35565286, 2022). "The tumor-infiltrating immune cells, including anti-cancer immune cells (CD4+ and CD8+ T cells, Th1 and Th2 cells, M1 macrophages, B cells, and pDCs were reflected in the score." (PMID 35945417, 2022). "While CD4+ Tregs have been a widely recognized regulator of the tumour immune microenvironment, more recently, CD8+ Tregs have also been identified, albeit with less definitive markers." (PMID 35158816, 2022). "IL-35 has been shown to act together with IL-10 in TME to induce BLIMP-1 mediated upregulation of inhibitory receptors on tumor-reactive CD4+ and CD8+ T cells." (PMID 36248808, 2022). "By blocking TGF-β signaling in CD4+ T cells, Th2 cells secrete IL-4, which reshapes the tumor immune microenvironment and suppresses tumor growth." (PMID 35684449, 2022). "VISTA is raised in tumor infiltration related cells, including T cells, especially in Tregs naïve CD4+ and CD8+ TCRαβ T cells, and TCRγδ T cells." (PMID 35831836, 2022). "A moderate correlation between frequencies of FoxP3+Helios+ Tregs and CD4+LAG-3+ T cells in in circulation was stronger in advanced tumor stages, compared to early stages (r = −0.146, p = 0.631 [early]; r = 0.478, p = 0.044 [advanced])." (PMID 36146549, 2022). "Despite activation in Tregs during the treatment, other anti-tumor T cells (CD8+ and CD4+) were more activated in the tumor microenvironment." (PMID 36276141, 2022). "Second, we did not evaluate the contribution of MHC-II restricted peptides and the role of CD4 T cells, which were recently shown to mediate and drive anti-tumor cytotoxicity and immunogenicity following ICB, also in UC59–61." (PMID 35410325, 2022). "TIL1383I is a prototypical class-mismatched TCR, cloned from a CD4+ T cell but recognizing the tyrosinase tumor antigen presented by the class I MHC HLA-A2 in a fully functional manner." (PMID 36424374, 2022). "Correlation analyses of YTHDF1, YTHDF2, and tumor infiltrating lymphocytes (CD4- and CD8-positive T cells and FOP3-positive T regulatory cells (Treg)) were performed on immunohistochemical and gene expression data." (PMID 36479088, 2022). "The cell cluster diagram of different samples showed that there were more NK cells and B cells infiltrating in healthy samples, but more CD4+T cells infiltrating in tumor samples." (PMID 36569220, 2022). "The majority of Ag-specific anti-tumor immune responses are carried out by type-1 cellular effectors, namely CD4+ Th1 cells and CD8+ CTLs." (PMID 35269457, 2022). "CD4 T cells play essential roles in anti-tumor immune responses by enhancing the influx, efficacy, and duration of CD8 T cell responses." (PMID 35565329, 2022). "In IHC staining analyses of the tumor tissue sections, we observed a higher microvascular density but a repressed level of CD4+ T cells from the tumors derived from Panc 02 plus rHSP90α-treated RAW264.7 cell grafts." (PMID 35053345, 2022). "CD4+CD25+Foxp3+ Tregs are the immunosuppressive cells related to the tumor progression, invasiveness, as well as metastasis." (PMID 35493518, 2022). "The competitive inhibitor 1-methyl-tryptophan (1-MT) in AML abrogates Treg induction by IDO+ tumor cells and promotes the expansion of CD4+CD25 T cells." (PMID 36230990, 2022). "Further, 12 CDR3s from CD8+ T cells and 23 CDR3s from CD4+ T cells ex vivo were also recovered in tumor tissue." (PMID 35361728, 2022). "An altered tumor microenvironment signature was also identified in GC samples with MUC16 mutations, as characterized by decreased infiltration of stromal cells, CD4+ T cells, and macrophages." (PMID 35211490, 2022).
tumor (continued). "While collaborations between CD8+IFNγ+ and CD4+IFNγ+ T cells are needed to kill tumor cells, several studies have reported that both of these cell types are suppressed in cancer patients during disease progression." (PMID 35053375, 2022). "IHC staining for CD8+ and CD4+ T cells was also performed on tumor sections resected on Days 7, 10, and 14 and scoring by a pathologist also led to similar results." (PMID 36176603, 2022). "There was a correlation between tumor-infiltrating immune cells (B cells, CD4+ T cells, CD8+ T cells, neutrophils, macrophages, and dendritic cells) and hub genes." (PMID 35093172, 2022). "Other therapies, such as tumor antigen-specific vaccines and immunocytokines, have been shown to activate and improve the recruitment of CD4+ and CD8+ T cells to the tumor, resulting in improved T effector to Treg ratio." (PMID 36159809, 2022). "Antigen-engaged CD4 +effectors correlate with tumor growth control, and depletion of Treg by addition of an anti-CD25 ICI, releasing suppression of conventional CD4 +effectors by Treg, enhances survival and activates immune signaling within tumors." (PMID 35338089, 2022). "CD4+ T cells were sorted from tumors and tumor-draining lymph nodes of Tslp transgenic (test) or Tslpr knockout (TslprKO, control) mice and stimulated ex vivo using anti-CD3/CD28 antibodies plus TSLP." (PMID 36467403, 2022). "Addition of PD-1 blockade to OT-I T cell therapy also increased tumor infiltration by endogenous CD4 T cells." (PMID 35793866, 2022). "Herein, we review the impact of tumor infiltrating lymphocytes (TILs), mainly the CD4+, CD8+, and regulatory T-cell (Tregs) responses on the course of MCC, including their role in initiating MCPyV-specific immune responses." (PMID 36551547, 2022). "A study showed that more TILs infiltrated the tumor environment in NSCLC when normally CD4+ T cells account for a large percentage." (PMID 35122478, 2022). "The FAS/FAS-L interaction in Bregs induces apoptosis in CD4+ T cells, while the same interaction also helps in killing tumor cells." (PMID 35746487, 2022). "Central to the complex immune response against cancer is the generation of tumour‐specific effector T cells, such as CD4+ helper T cells (TH) and CD8+ cytotoxic T cells (CTL), which mediate and influence tumour‐specific destruction." (PMID 35261190, 2022). "The tumour microenvironment (TME) in ALK rearranged cancers refers to the interplay of CD4 + T cells, CD8 + T cells, tumour associated macrophages (TAMs), mast cells and regulatory T cells (FOXP3 +)." (PMID 36591504, 2022). "Similar to other UV-induced tumors, PDS are inflammatory and immunogenic tumors (with a high number of CD4+/CD8+ tumor-infiltrating lymphocytes (TILs) and checkpoint molecule expression such as PD-L1, LAG-3, TIGIT) with a very high mutational burden." (PMID 36465341, 2022). "Tumors with a high RvD score displayed increased levels of anti-tumor effectors such as CD4+, CD8+ T lymphocytes, and decreased infiltration of plasma and dendritic cells." (PMID 35742918, 2022). "It is conceivable that C3 expressed in tumor cells can be cleaved inside these cells in non-C3 convertase fashion by cathepsins similar to cathepsin L in CD4+ T cells." (PMID 35860237, 2022). "Overall, the use of NF-αCTLA4 and NBTXR3 reduced Tregs in both primary and secondary tumors, and both in tandem did so while preserving CD4+ T cell levels and increasing cytotoxic T cell levels in the secondary tumor." (PMID 36405757, 2022). "Many of the current studies focus on the tumor-infiltrating lymphocytes (TILs) in the tumor microenvironment, a heterogeneous population including two distinct pools of effector (CD4+ T cells, CD8+ T cells, NK cells) and suppressor (Tregs) phenotypes." (PMID 35484541, 2022). "The association of the number of CD3+, CD4+ and CD8+ T cells infiltration in the local tumor microenvironment with preoperative NLR, PLR and LMR level was analyzed." (PMID 35719959, 2022).
tumor (continued). "Our results showed that CD4+ VISTA+ T cells were significantly increased in fresh NSCLC tumor tissues compared with peritumor tissues." (PMID 35122478, 2022). "Production of IL-21, CXCL13, and infiltration by cytolytic CD4 and CD8 T cell infiltrates associate with IMAE development in tumor models and human plasma." (PMID 36314014, 2022). "We found that higher frequencies of CD4+FoxP3+ Tregs in circulation were associated with shorter DFS, implicating the harmful effect of these suppressive cells in inhibiting anti-tumor immune responses in circulation." (PMID 35655158, 2022). "It is therefore likely that TGFβ blockade will cause expansion or de novo differentiation of these cytotoxic CD4+ T cells, thereby contributing to tumor cell killing." (PMID 36382146, 2022). "We compared proportions of CD3+, CD4+, and CD8+ T cells, CD57+ natural killer (NK) cells, CD4+ FOXP3+ regulatory T cells (Tregs), and CD68+ CD163+ M2 tumor-associated macrophages (TAMs) between paired ACC and SCCC samples, respectively." (PMID 36032124, 2022). "After CRISPR/Cas9 reduced the expression level of PD-L1 on tumor cells, CD4 T cells, CD8 T cells, NK cells and CD11c M1 macrophages increased significantly in the tumor microenvironment, while regulatory T cells decreased." (PMID 35300341, 2022). "Together, we have generated MHC class I-restricted tumor-specific CD4+ TCR-Ts that were capable of antitumor effector functions comparable to CD8+ TCR-Ts, such as secretion of inflammatory cytokines and direct lysis of target cells." (PMID 35928827, 2022). "Morphometric analysis indicated the significant increase of CD4+ and CD8+ lymphocytes density in the tumor side GBM (CD4+: 2.4 ± 0.33%, CD8+: 0.24 ± 0.04%), as compared to the CTRL (CD4+: 0.4 ± 0.02%; CD8+: 0.02 ± 0.001%)." (PMID 36611806, 2022). "In patients with PLC, T cell responses are strongly impaired, due to a highly suppressive tumor milieu and a reactivation of tumor-specific Th1 CD4 and CD8 T cell responses is indispensable to mediate control of liver cancer progression." (PMID 35173308, 2022). "But this is contrary to our common perception that activated T CD4+ memory cells can positively modulate immune function and inhibit tumor growth." (PMID 35494024, 2022). "IL-22 induces tumor-elicited inflammation from the T lymphocytes (CD4+ T cells) production via the activation of STAT3." (PMID 35563678, 2022). "We performed immunohistochemical staining of tumor material to detect CD4+ and CD8+ tumor infiltrating lymphocytes (TILs) as well as immunosuppressive markers such as PD-1 and PD-L1." (PMID 35158808, 2022). "This CD4+/CD8+ ratio decrease preceded the tumor mass’s transient disappearance at week 18, in which a concomitant CD4+/CD8+ ratio peak high was detected." (PMID 35323686, 2022). "Given the multifaceted roles of CD4 T cells in anti-tumor immune responses, we assessed their presence following the combo therapy." (PMID 36113478, 2022). "In TME, Tumor infiltrating T lymphocytes, mainly CD4+ and CD8+ T cells and their immunoregulatory cytokines define adaptive immunity." (PMID 36620544, 2022). "We observed tumor growth in both groups suggesting that both CD4 and CD8 T cells are responsible for the adaptive memory immune response observed." (PMID 36385142, 2022). "That is, the immune effector cells like CD8+ T cells, CD4+ Th, DCs, and NK cells which have anti-tumor effects are reduced in number, whereas immunosuppressive cells such as Tregs, M2 type TAMs, and MDSCs are present in large numbers." (PMID 35712476, 2022). "Id22, a peptide vaccine, was efficient enough to protect mice from the growth of MM, which induced antigen-specific CD4+ Th activity and anti-tumor immunity." (PMID 36263174, 2022).
tumor (continued). "Recent studies in three preclinical tumor models indicated that CD4 T cells play an important role in tumor control." (PMID 36569934, 2022). "Among these CD4+ T helper subsets, Th1 and Th17 have cytotoxic functions and have potential roles in anti-tumor immunity." (PMID 36231078, 2022). "It is plausible that MEKi, together with the abundance of CD4+ TILs, favors immunological pathways for qualitatively better tumor control." (PMID 35740548, 2022). "Along with spatial information, it will also be important to understand the molecular signals required to induce the recruitment and differentiation of CD4 Th cells into Tfh-like CD4 T cells in the tumor environment." (PMID 35937775, 2022). "In summary, Th1-dominant CD4+ T cells induced by cryo-thermal therapy orchestrated comprehensive and diverse endogenous antitumor immune memory to inhibit tumor metastasis." (PMID 35874660, 2022). "It has been proved that resting memory CD4+ T cells can regulate tumor growth, which corresponds to our findings." (PMID 35620481, 2022). "Compared to immune-activated samples, immunosuppressive samples showed higher tumor purity, lower immune/stromal scores, and lower expression of immune markers, as well as lower infiltration abundance of CD4+ T cells and CD8+ T cells." (PMID 35692574, 2022). "In contrast, Beff cells produce proinflammatory cytokines, including IL-6, IFNγ, and tumor TNFα, to stimulate memory and memory effector CD4+ T cell responses." (PMID 35267563, 2022). "Average light intensity determined that CD4 CAR T cell-treated mice had a 52% lower tumor burden relative to control on Day 6, whereas CD4-IL15/IL15sushi CAR T cells had a 74% lower tumor burden." (PMID 36172388, 2022). "With regards to CD4+ lymphocytes, a frequency reduction in Opn4WT tumor-bearing mice compared to Opn4KO and sham control mice was found." (PMID 35562405, 2022). "In tumour immunity, CD4+ T cells activate CD8+ T cells through various mechanisms and promote their differentiation into cytotoxic T lymphocytes (CTLs) to maintain and strengthen the antitumour response of CTLs." (PMID 34731284, 2022). "The highest density was found for CD8 cells in the invasive front, while the lowest density was found for CD4 cells in the tumor center." (PMID 36526699, 2022). "Memory T cells are reported to play roles in eliminating tumor cells and activated memory CD4 T cells indicate an improved survival in several cancers." (PMID 35804390, 2022). "While CD4+ memory resting T cells contribute most T-cells within the tumour microenvironment (TME), their presence is highly influenced by CCL2, ANG, CHI3L1, IL-6 and IL-8." (PMID 36430641, 2022). "Treatment with combination therapy increased the plasma concentrations of IFN-γ, TNF-α, IL-2, and IL-6, indicating that tumor-infiltrating Treg cells gained CD4 effector function." (PMID 36090972, 2022). "Studies have found that solanine can enhance the anti-tumor immune response by down-regulating CD4+CD25+Tregs in tumor tissue and down-regulating the expression of Foxp3 and TGF-β." (PMID 36278230, 2022). "Unlike CD8+ TEM cells, which are directly involved in mediating tumour apoptosis, CD4+ TEM cells play a supporting role, rapidly producing a cytokine response and reducing CD8+ T-cell exhaustion." (PMID 36289605, 2022). "The distribution of CD4+ T cell subtypes showed that the tumor tissues, compared to adjacent tissues, exhibited an enrichment of Tregs cells and a decline of memory cells." (PMID 36008393, 2022). "Tregs depletion enhanced their capacity to elicit strong CD4+ conventional T cells responses and ensuing anti-tumor protection." (PMID 35585567, 2022). "Another mechanism of tumor rejection that requires the interaction of CD4+ T cells and macrophages has been described in a series of studies by Bogen and colleagues." (PMID 36159781, 2022).